KDM3A (lysine demethylase 3A)
Description:
Histone demethylase that specifically demethylates 'Lys-9' of histone H3, thereby playing a central role in histone code. Preferentially demethylates mono- and dimethylated H3 'Lys-9' residue, with a preference for dimethylated residue, while it has weak or no activity on trimethylated H3 'Lys-9'. Demethylation of Lys residue generates formaldehyde and succinate. Involved in hormone-dependent transcriptional activation, by participating in recruitment to androgen-receptor target genes, resulting in H3 'Lys-9' demethylation and transcriptional activation. Involved in spermatogenesis by regulating expression of target genes such as PRM1 and TNP1 which are required for packaging and condensation of sperm chromatin. Involved in obesity resistance through regulation of metabolic genes such as PPARA and UCP1.
Synonyms: JHDM2A; JMJD1; JMJD1A; KIAA0742; TSGA; JHMD2A
Tractability: Small molecule: a high-quality ligand is known. PROTAC: ubiquitination databases record sites on it; its protein half-life has been measured; a small molecule that binds it is known.
Target class: Epigenetic regulator; Jumonji domain-containing; Eraser; Lysine demethylase
Chemical probes: IOX1 (high quality)
Gene: Protein-coding gene on chromosome 2 (86,440,647 to 86,492,716, forward strand). Ensembl gene ENSG00000115548.
Subcellular location: Cytoplasm; Nucleus
Subcellular location (Human Protein Atlas): Nucleoplasm
Pathways (Reactome):
Chromatin organization: HDMs demethylate histones
Signal Transduction: NR1H3 & NR1H2 regulate gene expression linked to cholesterol transport and efflux
Gene Ontology:
Molecular function: histone H3K9 demethylase activity; histone H3K9me/H3K9me2 demethylase activity; iron ion binding; nuclear androgen receptor binding; protein binding; transcription coregulator activity; chromatin binding
Biological process: androgen receptor signaling pathway; formaldehyde biosynthetic process; hormone-mediated signaling pathway; positive regulation of DNA-templated transcription; positive regulation of cold-induced thermogenesis; regulation of transcription by RNA polymerase II; chromatin remodeling
Cellular component: membrane; nucleoplasm; nucleus; histone deacetylase complex; cytoplasm
Genetic constraint (gnomAD): Loss-of-function variants: 51 observed, 137.34 expected, observed/expected ratio (o/e) 0.37, 90% interval 0.3 to 0.47. The upper end of that interval is the gene's LOEUF score, 0.47, which puts it in group 2 of 6, group 1 being the genes least tolerant of losing a copy. Missense variants: 1,152 observed, 1,446.1 expected, observed/expected ratio (o/e) 0.8, 90% interval 0.76 to 0.84. Synonymous variants: 552 observed, 520.17 expected, observed/expected ratio (o/e) 1.06, 90% interval 0.99 to 1.14.
Homologues: Orthologues: chimpanzee KDM3A (99% identical), macaque KDM3A (98% identical), pig KDM3A (94% identical), dog KDM3A (94% identical), rabbit KDM3A (92% identical), rat Kdm3a (92% identical), mouse Kdm3a (92% identical), guinea pig KDM3A (88% identical), tropical clawed frog kdm3a (59% identical), Drosophila melanogaster Kdm3 (26% identical). Paralogues in human: KDM3B (49% identical), JMJD1C (38% identical), HR (18% identical).
Diseases named in the same sentence as KDM3A in open-access papers:
KDM3A is named in the same sentence as 111 diseases in open-access papers, as found by Europe PMC text mining. Sharing a sentence is not in itself a finding about the gene and the disease. The quoted sentences say what the papers report.
breast carcinoma (24 papers, 2015 to 2024). "Future challenges are to identify factors that directly regulate the production of KDM3A, and to understand how these factors are manipulated in breast cancer cells to cause anoikis resistance." (PMID 27472901, 2016). "While an increase of KDM3A is concomitant with a reduced H3K9me2/3 during breast tumorigenesis, KDM3A facilitated the activation of genes implicated in breast cancer as MYC, PAX3, Cyclin D1, MMP-9, S100A4, and JUN, thereby enhancing the proliferation and motility of breast cancer cells." (PMID 36185256, 2022). "KDM3A is expressed in BCa tissue and it has been reported following study of The Cancer Genome Atlas (TCGA) human breast cancer database (n = 729) that patients with BCa expressing high levels of KDM3A had a 3-fold increased risk of death than those with normal or low KDM3A expressing disease." (PMID 25488809, 2015). "Exampled by a recent report, the invasive ability of breast cancer cells manifesting inhibited KDM3A is impaired in hypoxia." (PMID 34044859, 2021). "Mahajan and colleagues reported that Ack1 can interact with the estrogen receptor (ER)/histone demethylase KDM3A (JHDM2a) complex and promote the growth of tamoxifen-resistant breast cancer through epigenetic regulation." (PMID 32404161, 2020). "To date, it has been found that ACK1 interacts with a variety of receptor tyrosine kinases (EGFR), oncoproteins (AKT), tumor suppressor proteins (Wwox), and epigenetic modification regulatory proteins (KDM3A) in breast cancer." (PMID 31772931, 2019). "Thirdly, we found that KO of Kdm3a in the mammary tumor cells decreased cyclin D1 expression and tumor cell proliferation, suggesting that Kdm3a also up regulates cyclin D1 expression and promotes cell proliferation in breast cancer cells." (PMID 29156681, 2017). "A similar overlapping network of KDM3A demethylation, nuclear hormone signaling, and hypoxia is described in estrogen independent breast cancer models." (PMID 28416760, 2017). "In this study, we assessed the role of Kdm3a in mammary gland tumorigenesis by comparing the latencies and growth rates of mammary tumors induced by RCAS-PyMT virus in WT and Kdm3a KO mice." (PMID 29156681, 2017). "To investigate the role of Kdm3a in modifying cyclin D1 expression in the mammary tumor cells, we measured cyclin D1 mRNA and protein expression by real-time polymerase chain reaction (QPCR) and IHC." (PMID 29156681, 2017). "We further found that KDM3A/JMJD1A is much higher in two breast cancer cell lines, MCF and T47D, than that in the primary HMC and other two cancer cell lines, HCT116 and 769-P." (PMID 27034728, 2016). "A commercial breast tissue array containing 48 pairs was stained with KDM3A and the statistical analysis showed that KDM3A significantly increases in breast cancer tissues compared with normal tissues." (PMID 27034728, 2016). "To further explore the function of KDM3A/JMJD1A in breast cancer transformation, we made KDM3A stable knockdown cell lines in HMC-L and HMC-LT." (PMID 27034728, 2016). "Using mouse models of breast cancer metastasis we show that knockdown of Kdm3a enhances metastatic potential." (PMID 27472901, 2016). "Our study demonstrates reduction of histones H3K9 me2 and me3, and elevation of KDM3A/JMJD1A as important events for breast cancer, and illustrates the dynamic epigenomic mechanisms during breast cancer transformation." (PMID 27034728, 2016). "The results suggested KDM3A/JMJD1A regulates the tumorigenesis of breast cancer through down-regulating H3K9me2 on oncogenes MYC and PAX3." (PMID 27034728, 2016).
breast carcinoma (continued). "Additionally, Kdm3a has been found to influence estrogen signaling, particularly in its role in the effectiveness of ER signaling in breast cancer cells, suggesting a role in mediating the effects of both sex hormones on gene expression." (PMID 39857659, 2024). "Therefore, in this study, lentivirus-mediated knockdown of KDM3A using short hairpin RNA was employed, and fluorescence imaging and tumor weight measurements were evaluated in a mouse model of mammary tumors." (PMID 38165573, 2024). "KDM3A is overexpressed in breast cancer tissues and our previous siRNA screening indicated that it may be important for TNBC cell growth." (PMID 34779768, 2021). "Also, activity of histone demethylase KDM3A has been found to play an important part in the mediation of oncogene HOXA1 expression in breast cancer." (PMID 33520978, 2020). "Especially, KDM3A loss in ovarian cancer induces replicative senescence and cell cycle arrest but no such effects were seen in breast cancer cells." (PMID 27694900, 2017). "In human breast cancer cells, knockdown or inactivation of KDM3A abolished the recruitment of estrogen receptor alpha (ERα) to its target gene enhancer/promoter regions, leading to a downregulation of ERα target genes and attenuated response to estrogen-stimulated cell growth." (PMID 29156681, 2017). "Furthermore, KO of Kdm3a also significantly slows down the polyoma middle T (PyMT) oncogene-induced mammary tumor growth by reducing cyclin D1 expression and cell proliferation." (PMID 29156681, 2017). "However, KDM3A levels are low in human breast cancers, which suggests that these cancers become resistant to anoikis by preventing increases in KDM3A production." (PMID 27472901, 2016). "Importantly, the catalytic activity of KDM3A is crucial for both ER-target gene expression and cell proliferation in breast cancer." (PMID 25488809, 2015). "To assess whether Kdm3a could directly promote cyclin D1 expression at the transcriptional level, we performed ChIP assay to examine if Kdm3a was recruited to the 5’ regulator sequence of the cyclin D1 gene containing the cyclin D1 promoter in MCF-7 human breast cancer cells." (PMID 29156681, 2017). "Finally, we find defective KDM3A expression in human breast cancer cell lines and tumors." (PMID 27472901, 2016). "We then asked whether KDM3A/JMJD1A elevation also occurs in breast cancer patients." (PMID 27034728, 2016). "The present study provides evidence of a co-operative role between the histone demethylase enzymes KDM3A and KDM4B in regulating ER-signalling in models of breast cancer." (PMID 31390833, 2019). "Overall, the identification of a KDM3A/KDM4B co-regulatory axis that regulates FOXA1 and subsequent ER deposition on chromatin in breast cancer enhances the understanding of the mechanisms controlling ER-transcriptional activity." (PMID 31390833, 2019). "Taken together, these data show that histone H3K9 demethylase, KDM3A/JMJD1A, increases in breast cancer cell lines." (PMID 27034728, 2016). "While we are submitting the manuscript, one group reported that KDM3A/JMJD1A regulates the expression of ER target genes in breast cancer cells, which supports our discovery of KDM3A/JMJD1A’s role in breast cancer." (PMID 27034728, 2016). "Finally, we show that depletion of both KDM3A and KDM4B has a greater inhibitory effect on ER activity and cell growth than knockdown of each individual enzyme, suggesting that targeting both enzymes represents a potentially efficacious therapeutic option for ER-driven breast cancer." (PMID 31390833, 2019).
prostate carcinoma (22 papers, 2015 to 2024). A carcinoma that arises from epithelial cells of the prostate gland. "Following characterization of histone H3K9me1/2 marks we determined enrichment of transcriptional motifs associated with these histone marks controlled by KDM3A in prostate cancer cells." (PMID 28416760, 2017). "Increased levels of both total and K421-acetylated KDM3A have been reported in prostate cancer cells resistant to the AR antagonist enzalutamide." (PMID 39394462, 2024). "This is particularly relevant in the context of prostate cancer, where Kdm3a regulates the transcriptional program of AR, facilitating tumor growth and progression." (PMID 39857659, 2024). "Treatment of enzalutamide-resistant prostate cancer cells with inhibitors of either p300 or BET was shown to destabilize KDM3A, conferring sensitivity to the AR antagonist." (PMID 39394462, 2024). "We matched transcriptomic and ChIP-Seq profiles to decipher a genome-wide regulatory network of epigenetic control by KDM3A in prostate cancer cells." (PMID 28416760, 2017). "KDM3A controlled H3K9me1/2 ChIP-Seq data shows a strong enrichment of AR binding sites within the CWR22Rv1 castration-resistant prostate cancer cell line with continued expression of genes involved in the androgen response." (PMID 28416760, 2017). "In conclusion, the ChIP-Seq study refined the genomic sites of KDM3A-mediated H3K9me1/2 histone demethylation within the CWR22Rv1 prostate cancer cell line." (PMID 28416760, 2017). "In prostate cancer cell lines, KDM3A promotes androgen receptor activity that in turn upregulates c-Myc expression and also inhibits the E3 ubiquitin ligase HUWE1 which prevents c-Myc protein degradation." (PMID 29156681, 2017). "It has been reported that Kdm3a can work with androgen receptor to upregulate c-Myc expression in prostate cancer cells." (PMID 29156681, 2017). "The ability to cooperate with the AR highlights a potential role of KDM3A as coactivator and driving force for sex-specific tissue development as well as for prostate cancer initiation and progression." (PMID 28416760, 2017). "Additional studies of KDM3A revealed that its demethylation of H3K9me2/1 facilitates the transcriptional activity of AR, and HIF1α in responding to hypoxia in prostate cancer cells." (PMID 27689328, 2016). "KDM3A influences the regulation of DNA damage response genes and enhances the chromatin recruitment of c‐Myc in prostate cancer through H3K9me3 demethylation.[10b] Furthermore, targeting KDM3A has the potential to sensitize prostate cancer cells to treatment by inhibiting androgen receptor activity." (PMID 39031630, 2024). "A histone demethylase KDM3A has been revealed to transcriptionally activate Snail expression via H3K9me1 and H3K9me2 demethylation at its special promoter region, consequently promoting prostate cancer progression." (PMID 35395834, 2022). "Using this data we defined the set of 56.9% differentially expressed genes as positively regulated by KDM3A activity (down in the CRL-2505 prostate cancer line with shRNA knockdown of KDM3A), and 43.1% of differentially expressed genes as negatively regulated by KDM3A activity." (PMID 29977600, 2018). "Transcriptomic impact of 4326 differentially expressed genes upon KDM3A knockdown showed 2460 genes as positively regulated by KDM3A activity (down in the CRL-2505 prostate cancer line with shRNA knockdown of KDM3A), and 1866 genes as negatively regulated by KDM3A activity." (PMID 29977600, 2018). "Previous studies have outlined KDM3A expression levels in prostate cancer phenotypes, but KDM3A-regulated target pathways by ChIP-Seq analysis were unknown." (PMID 28416760, 2017). "Interestingly, KDM3A knockdown in other prostate cancer cell lines, including the androgen dependent LNCaP cells, blocked cell proliferation." (PMID 28416760, 2017). "KDM3A also regulates androgen receptor (AR) activity in prostate cancer cell lines." (PMID 25488809, 2015).
prostate carcinoma (continued). "Nonetheless, KDM3A/JMJD1A and KDM4C/JMJD2C were suggested to be hypoxia-inducible genes in kidney and prostate cancer cell lines." (PMID 31739546, 2019). "For instance, the JmjC-domain-containing protein JHDM2A/KDM3A, that specifically demethylates histone H3 at lysine 9 (H3K9), is iron-dependent and regulates androgen receptor transcription in prostate cancer cells." (PMID 30591630, 2018). "KDM3A removes transcriptionally repressive mono- and di-methyl marks from H3K9 and has been shown to be required for successful AR recruitment to AR-target gene promoters in prostate cancer cell lines upon ligand stimulation." (PMID 25488809, 2015).
colorectal cancer (21 papers, 2014 to 2025). A primary or metastatic malignant neoplasm that affects the colon or rectum. "A carboxamide-substituted benzhydryl amine, CBA-1, functions as a KDM3A/3B inhibitor (typically inhibiting KDM3A), causes increased levels of H3K9me2, inhibits Wnt targets (Axin2, c-Myc, and Cyclin B1), and prevents colorectal cancer cell proliferation." (PMID 37218871, 2023). "In colorectal cancer, KDM3A depletion causes H3K9me2 up-regulation mainly on TEAD1-binding enhancers rather than gene bodies, further resulting in H3K27ac decrease, less TEAD1 binding on enhancers and transcription impair." (PMID 35269968, 2022). "It is interesting to note that KDM3A and p300 have been shown to physically associate in colorectal cancer." (PMID 35625569, 2022). "miR-22-3p was also reduced in colorectal cancer patients and inhibited the cancer malignancy through inhibition of KDM3A." (PMID 37620594, 2023). "Specifically, in studying the role of KDM3A/B in human colorectal cancer stem cells (CSCs), it was found that these demethylases recruit MLL1 to specific gene promotors to facilitate Wnt target gene activation." (PMID 35625569, 2022). "And KDM3A also functioned as oncogene to regulate colorectal cancer cell migration and invasion through modulating Epithelial–Mesenchymal Transition (EMT) and matrix metalloproteinases (MMPs)." (PMID 36008383, 2022). "Study has confirmed that KDM3A, which is highly expressed in colorectal cancer, is conducive to metastasis of colorectal cancer." (PMID 34980950, 2021). "For instance, KDM3A expression was notably increased in colorectal cancer metastatic lesions and its high expression was correlated with poor prognosis and short overall survival of colorectal cancer patients." (PMID 33350586, 2021). "We utilized shRNA to stably knockdown KDM3A/B expression in a human colorectal cancer cell line HCT116." (PMID 28440295, 2017). "Kdm3a has been shown to promote several types of cancers including colorectal carcinomas, neuroblastoma, hepatocellular carcinoma and sarcoma." (PMID 29156681, 2017). "Similarly, upregulation of KDM3A was found to be correlated with poor prognosis in other malignancies such as pancreatic cancer and colorectal cancer." (PMID 35590288, 2022). "Another study showed that KDM3A/B were recruited to Wnt target gene promoters in colorectal carcinoma (CRC) cells, and they contributed to transcriptional gene activation by demethylating H3K9me2/3." (PMID 40940894, 2025). "Notably, the role of KDM3A in colorectal cancer also directly involves MLL1." (PMID 35625569, 2022). "Lysine demethylase 3A (KDM3A), MAPK kinase and USP47 bolster YAP stability in colorectal cancer, while miR‐195‐5p inhibits YAP expression." (PMID 40066231, 2025). "In particular, in colorectal cancer, PHF5A acetylation strengthened the interaction among U2 snRNPs and enhanced the alternative splicing-mediated upregulation of KDM3A to promote colorectal cancer tumorigenesis." (PMID 37434235, 2023). "KDM3A/B substantially regulates the expression of Wnt or beta-catenin target genes c-Myc, MMP9 (matrix metallopeptidase 9), and cyclin D1 in colorectal cancer, thereby promoting the ability of colorectal cancer stem cells to undergo self-renewal." (PMID 37218871, 2023). "Similarly, nuclear co-IP assays in the human colorectal cancer cell line HCT116 verified the interaction between endogenous β-catenin and KDM3A or KDM3B." (PMID 28440295, 2017). "Importantly, KDM3A has been shown to upregulate YAP1 and the Hippo pathway in colorectal cancer." (PMID 33888871, 2022).